USP13 (ubiquitin specific peptidase 13)
Diseases named in the same sentence as USP13 in open-access papers (continued):
Sharing a sentence is not in itself a finding about the gene and the disease.
Hepatic steatosis (2 papers, 2024 to 2025). Steatosis is a term used to denote lipid accumulation within hepatocytes. "Moreover, the hepatic sections of USP13-KO mice exhibited increased lipid accumulation and inflammation under Oil Red O in combination with H&E staining, which suggests the deficiency of USP13 aggravate liver steatosis and inflammation." (PMID 39033101, 2024). "Moreover, inhibiting the phosphorylation of TAK1 reversed the aggravation of hepatic steatosis and inflammation induced by USP13 deficiency." (PMID 39033101, 2024). "USP13 overexpression significantly improved insulin resistance, hepatic steatosis and inflammation in HFD-fed and ob/ob mice." (PMID 39033101, 2024). "All above results further demonstrated the protective role of USP13 against hepatic steatosis, liver impairment and inflammation." (PMID 39033101, 2024). "These phenotype alterations indicated the role of USP13 in attenuating inflammation, insulin resistance, and liver steatosis in NAFLD." (PMID 39033101, 2024). "Liver steatosis, insulin resistance and inflammation were alleviated by hepatic USP13 overexpression in obese mice, and aggravated in USP13 knockout HFD-induced mice." (PMID 39033101, 2024). "USP13 overexpression by injecting with AAV8-USP13 via tail vein mitigated liver steatosis, inflammation, and insulin resistance in ob/ob and HFD-fed mice." (PMID 39033101, 2024). "By modulating TAK1 ubiquitination and phosphorylation, USP13 influences key signaling pathways involved in hepatic steatosis and inflammation." (PMID 39033101, 2024). "To summarize, USP13 suppressed liver steatosis, inflammation, and insulin resistance to demonstrate efficacy in treating ob/ob mice." (PMID 39033101, 2024). "Consistently, the in vivo experiments showed that USP13 overexpression ameliorated hepatic steatosis and metabolic disorders in HFD-fed mice, while its deficiency led to contrary outcomes." (PMID 39033101, 2024). "In addition, the TAK1 downstream IKKβ–P65 axis has been reported to be activated under insulin resistance in addition to liver steatosis; it was shown that activation of the IKKβ–P65 axis was reduced by USP13 overexpression." (PMID 39033101, 2024). "Notably, overexpressing of USP13 also markedly alleviated hepatic steatosis and inflammation in ob/ob mice." (PMID 39033101, 2024). "Gradual decrease in protein expression of deubiquitinating enzyme USP13 in hepatic tissue samples from human subjects without hepatic steatosis, with hepatic steatosis, and NASH." (PMID 40292292, 2025).
liver cancer (2 papers, 2022 to 2025). An epithelial or non-epithelial malignant neoplasm that arises from the liver. "Our research demonstrates that USP13 is highly expressed in liver cancer; however, the underlying cause of this elevated expression remains unclear." (PMID 41330897, 2025). "And consistent with our previous findings from 2-Met treatment, knockdown of USP13 significantly promoted liver cancer cell death in co-culture with T cells and inhibited cell proliferation." (PMID 41330897, 2025). "In addition, studies have shown that USP13 can affect the growth of liver cancer cells by regulating the expression of c-Myc." (PMID 35875077, 2022). "These in vitro and in vivo findings indicate that USP13 enhances the infiltration and activation of CD8 + T cells in liver cancer, thereby contributing to tumor suppression." (PMID 41330897, 2025). "These in vitro and in vivo findings indicate that USP13 enhances the infiltration and activation of CD8 + T cells in liver cancer depends on cholesterol, thereby contributing to tumor suppression." (PMID 41330897, 2025). "USP22, USP14, USP10, USP13, USP7, USP2, and USP8, liver cancer-related DUBs, have also been reported to have related small molecule inhibitors, but the research and development are not mature enough." (PMID 35875077, 2022).
lymph node metastasis (2 papers, 2022). "USP13 expression was found to be associated with lymph node metastasis and Gleason’s score." (PMID 36564767, 2022). "Logistic regression analysis showed that USP13 expression was correlated with lymph node metastasis." (PMID 36564767, 2022). "Next, we found that USP13 was significantly upregulated in the tissues of SCLC patients with lymph node metastasis." (PMID 35898882, 2022).
osteoarthritis (2 papers, 2023 to 2025). A noninflammatory degenerative joint disease occurring chiefly in older persons, characterized by degeneration of the articular cartilage, hypertrophy of bone at the margins and changes in the synovial membrane. "One of the Ub-specific processing proteases (USP13) can ameliorate osteoarthritis by restraining oxidative stress and inflammation." (PMID 40224608, 2023). "USP13 directly binds to and stabilizes PTEN, which alleviates inflammation, apoptosis, and oxidative stress in osteoarthritis." (PMID 41004574, 2025).
osteosarcoma (2 papers, 2023 to 2025). A usually aggressive malignant bone-forming mesenchymal neoplasm, predominantly affecting adolescents and young adults. "In osteosarcoma, Spautin-1–mediated inhibition of USP13 degrades METTL3, destabilizing ATG5 mRNA and impairing autophagy and glycolysis, which ultimately suppresses tumor growth." (PMID 40370434, 2025). "USP13 was found to upregulate in osteosarcoma (OS) specimens and promote OS progression through regulating aerobic glycolysis." (PMID 37151889, 2023).
Parkinson disease (2 papers, 2022 to 2024). A progressive degenerative disorder of the central nervous system characterized by loss of dopamine producing neurons in the substantia nigra and the presence of Lewy bodies in the substantia nigra and locus coeruleus. "USP13 is a de-ubiquitinase that controls the protein ubiquitination cycle and is overexpressed in the brains of patients with AD and Parkinson’s disease." (PMID 38890712, 2024). "USP13 levels are upregulated in post-mortem Parkinson’s disease, whereas USP13 knockdown via shRNA reduces alpha-synuclein levels in animal models." (PMID 35897705, 2022). "Ubiquitin-Specific Protease (USP)-13 is critical in the regulation of protein clearance mechanisms in models of Parkinson’s disease (PD)." (PMID 35897705, 2022).
prostate tumor (2 papers, 2022 to 2026). "Notably, inhibition of USP13 significantly decreases prostate tumor growth and improves enzalutamide treatments through PCMT1 suppression." (PMID 42056074, 2026). "The expression of USP13 was found to be significantly upregulated in 496 PCa tumor tissues compared with 152 normal tissue samples, and a similar result was observed when comparing USP13 expression in 52 pairs of prostate tumor and adjacent normal prostate epithelial tissues." (PMID 36564767, 2022).
squamous carcinoma (2 papers, 2021 to 2023). "In the KPU model, USP13 overexpression in club cells led to squamous cell carcinoma development in the KP genetic alteration background." (PMID 38093367, 2023). "Interestingly, USP13 sits on chromosome 3q26.33, in the so-called 3q26 ‘OncCassette’, a common amplicon that is found in most squamous cell carcinomas and includes the oncogene PIK3CA." (PMID 33627786, 2021). "We found that USP13 altered lineage-determining factors such as NKX2-1 and SOX2 in club cells of the airway and reinforced the fate of club cells to squamous carcinoma development." (PMID 38093367, 2023).
thyroid cancer (2 papers, 2022 to 2024). "Also, in vitro results indicated USP13 knockdown decreased thyroid cancer cell proliferation while USP13 c.1483G>A variant increased colony formation." (PMID 36188217, 2022). "Recently, a USP13 missense mutation was described in FNMTC, suggesting a potential involvement in thyroid cancer." (PMID 38338801, 2024).
ZIKV infection (2 papers, 2024 to 2025). "Integrating the 49-plex ELISA and RNA-Seq data, we observe 27 of the 49-plex proteins to be significantly differently expressed or secreted by USP7 or USP13 following ZIKV infection." (PMID 40240536, 2025). "Reduction of tumor growth ratio in USP7-ATRT and USP13-MED was also observed, even though DAOY cell line had a poor response to ZIKV infection, which fits in vitro findings." (PMID 39347716, 2024).
adenoma (1 paper, 2009). A neoplasm arising from the epithelium. "Except for NR2F2 (p<0.954), all genes were differentially expressed not only between the three subclasses of adenomas (t-test, p<0.05), but also between the four groups of follicular tumors (F-tests, p<0.05 for ADAMTS2, CABIN1, ALDH13, USP13; p = 0.06 for KRTHB5)." (PMID 19893615, 2009).
alpha-synucleinopathies (1 paper, 2022). "We synthesized novel small molecules, including BK50118-C, that are potent inhibitors of USP13 that effectively reduced alpha-synuclein levels and protected against neuronal death in models of alpha-synucleinopathies." (PMID 35897705, 2022). "USP13 inhibition may prevent de-ubiquitination of alpha-synuclein and limit its aggregation via the promotion of autophagy and proteasome clearance; thus, USP13 inhibitors may provide therapeutic agents in alpha-synucleinopathies." (PMID 35897705, 2022).
Anxiety (1 paper, 2022). Intense feelings of nervousness, tension, or panic often arise in response to interpersonal stresses. "USP13+/+ mice displayed both motor and behavioral symptoms, suggesting increased levels of anxiety when challenged with human alpha-synuclein." (PMID 35897705, 2022).
basal cell carcinoma (1 paper, 2023). A carcinoma involving the basal cells. "Ingenuity pathway analysis (IPA) of KP and KPU transcriptomes indicated that USP13 overexpression led to alteration of gene expression related to CREB signaling, basal cell carcinoma signaling, stem cell pluripotency, and EMT." (PMID 38093367, 2023).
bladder tumors (1 paper, 2019). "Expression of USP13 in normal bladder tissue and bladder tumor tissues based on individual stages (TCGA)." (PMID 31200745, 2019). "Expression of USP13 in normal bladder tissues and bladder tumor tissues from TCGA dataset." (PMID 31200745, 2019).
brain tumour (1 paper, 2025). "To investigate this, we infected and performed RNA-Seq on USP7 (P7) and USP13 (P13) brain tumour cells for 12, 18, and 24 h." (PMID 40240536, 2025). "None of the recombinant TNF proteins were cytotoxic, and TNF-alpha significantly increased both USP7 and USP13 confluence, indicating that soluble TNF-alpha enhances brain tumour cell growth." (PMID 40240536, 2025). "Multiple cell cycle, DNA replication and DNA repair terms are significantly upregulated specifically in USP13 cells during 12–18 hpi, whereas cell cycle-related terms are significantly downregulated in USP7 at 24 hpi; indicating that ZIKV may differentially regulate brain tumour cell growth." (PMID 40240536, 2025).
breast tumors (1 paper, 2015). "Zhang and colleagues have demonstrated that USP13 expression was reduced in human breast tumors and that USP13 depletion could promote tumorigenesis through the down-regulation of PTEN." (PMID 26453058, 2015).
colitis (1 paper, 2025). Inflammation of the colon. "This study investigated the regulatory role of a deubiquitinase ubiquitin-specific peptidase 13 (USP13) in a DSS-induced colitis mouse model and explored the underlying mechanism." (PMID 40679368, 2025). "The results show that intestinal epithelial-specific USP13 knockout exacerbated DSS-induced colitis, linked to increased ER stress and apoptosis." (PMID 40679368, 2025). "Intestinal epithelial-specific Usp13 knockout (USP13IEKO) mice were treated with DSS to induce colitis." (PMID 40679368, 2025). "Moreover, restoration of USP13 expression via AAV9 in USP13IEKO mice attenuated DSS-induced colitis and preserved intestinal barrier integrity." (PMID 40679368, 2025).
colon adenocarcinoma (1 paper, 2025). "To investigate the clinical relevance of USP13 in CRC, we analyzed transcriptomic data from public databases and found that USP13 was significantly upregulated in colon adenocarcinoma (COAD) from the GEPIA2 (Gene Expression Profiling Interactive Analysis)." (PMID 41307804, 2025).
colon carcinoma (1 paper, 2019). "We first observed that protein and mRNA levels of USP11, but not any other known PTEN DUBs (such as HAUSP, USP13, and OTUD3), were markedly lower in isogenic PTEN-null (PTEN-/-) HCT116 colon carcinoma cells compared to WT parent (PTEN+/+) or heterozygous (PTEN+/-) cells." (PMID 30733438, 2019).
Insulin resistance (1 paper, 2024). Increased resistance towards insulin, that is, diminished effectiveness of insulin in reducing blood glucose levels. "In conclusion, our study identifies USP13 as a crucial regulator of insulin resistance and inflammation in NAFLD through its interaction with TAK1." (PMID 39033101, 2024).
intervertebral disc degeneration (1 paper, 2022). "Studies have shown that the YQHR promotes the formation of the Beclin1-VPS34 complex through the upregulation of deubiquitinase USP13 and the activation of AMPK to activate autophagy and inhibit cell apoptosis, thereby alleviating intervertebral disc degeneration development." (PMID 35615578, 2022).
kidney cancer (1 paper, 2023). Primary or metastatic malignant neoplasm involving the kidney. "USP13 mediates the deubiquitination of ZHX2 and promotes tumorigenesis in kidney cancer." (PMID 37259026, 2023).
lipid metabolism disorders (1 paper, 2024). "The number of studies related to lipid metabolism disorders related to USP13 is limited." (PMID 39033101, 2024).
multiple sclerosis (1 paper, 2013). A progressive autoimmune disorder affecting the central nervous system resulting in demyelination. "Exceptional PD-related examples of seemingly active miRNA-spliced transcripts predicted interactions include USP13, which promotes smooth (SMO) signaling by preventing its ubiquitination, RGS3 which contributes to neural progenitor/stem cell regulation and MGAT1, involved in multiple sclerosis." (PMID 23717260, 2013).
nonalcoholic steatohepatitis (1 paper, 2025). "USP13 ameliorates nonalcoholic steatohepatitis by targeting Irhom2 or TAK1." (PMID 41004574, 2025).
Obesity (1 paper, 2025). Accumulation of substantial excess body fat. "Consistently, in mouse adipose tissue, the mRNA and protein levels of USP10 were increased in obesity, whereas USP13 revealed a high Ct by RT-qPCR and was undetectable by immunoblot, which aligns with FANTOM5 (FF:10010-101C1)." (PMID 41417444, 2025). "To test this hypothesis, we integrated the mining of public adipose-tissue datasets with in vitro adipocyte differentiation assays, pharmacologic perturbation, and the genetic manipulation of USP10/USP13 and evaluated the anti-obesity efficacy in a high-fat diet mouse model." (PMID 41417444, 2025). "Analysis of publicly available RNA-sequencing datasets (GSE213058 and GSE235696) revealed that USP10, but not USP13, was elevated in adipose tissue from adults with obesity compared with that of lean controls, with a bias toward VAT over SAT." (PMID 41417444, 2025).
ovarian serous cystadenocarcinoma (1 paper, 2022). A malignant serous cystic epithelial neoplasm arising from the ovary. "Analysis of TCGA data indicates that USP13 is rarely mutated, but the USP13 gene is highly amplified (19.5% Amp) or gained (58.5 % Gain) in human ovarian serous cystadenocarcinoma." (PMID 35173307, 2022).
peritonitis (1 paper, 2025). Inflammation of the peritoneum (tissue that lines the abdominal wall and covers most of the organs in the abdomen). "In particular, USP13 ablation in mice attenuated MSU-induced peritonitis, as manifested by decreased IL-1β release and inflammatory cell infiltration." (PMID 41004574, 2025). "The MSU-induced peritonitis model was used to investigate the regulatory role of USP13 in the activation of the NLRP3 inflammasome in vivo, which is a well-established NLRP3-dependent acute inflammatory model characterized by IL-1β secretion and massive neutrophil influx into the peritoneal cavity." (PMID 41004574, 2025). "USP13 deletion mice are resistant to MSU-induced peritonitis." (PMID 41004574, 2025).
primary brain tumors (1 paper, 2023). "We identified a selected group of DUBs (USP13, USP14, USP19, USP25, OTUD2/YOD1) associated with the Regulation of ERAD pathway across several adult and pediatric primary brain tumors (GBM, EPN, CPh, MB)." (PMID 37892185, 2023).
renal carcinoma (1 paper, 2024). A carcinoma arising from the epithelium of the renal parenchyma or the renal pelvis. "Interestingly, USP13 has also been implicated in renal cancer, but rather than altering HIF activity, USP13 deubiquitinates another VHL target gene and oncogenic driver, ZHX2." (PMID 39584532, 2024).
sarcoma (1 paper, 2023). A usually aggressive malignant neoplasm of the soft tissue or bone. "Also, results from another online database further confirmed that patients with high USP13 expression in sarcoma had a poorer prognosis." (PMID 37151889, 2023).
ulcerative colitis (1 paper, 2025). An inflammatory bowel disease involving the mucosal surface of the large intestine and rectum. "Also, USP13 levels were reduced in ulcerative colitis patients compared to the healthy controls, highlighting its protective role in intestinal health." (PMID 40679368, 2025).